GRK2 (G protein-coupled receptor kinase 2)
Diseases named in the same sentence as GRK2 in open-access papers (continued):
Sharing a sentence is not in itself a finding about the gene and the disease.
Hypertension (32 papers, 2014 to 2025). The presence of chronic increased pressure in the systemic arterial system. "shRNA-induced total body knockdown of GRK2 causes spontaneous hypertension and impairs vascular reactivity." (PMID 38961282, 2024). "We have also reported that exposure to maternal diabetes mellitus causes renal D1R dysfunction and hypertension in adult rat offspring by increasing GRK2 activity." (PMID 38961282, 2024). "This is similar to the findings of another study in which Grk2 knockdown in mice exacerbates kidney injury and causes spontaneous hypertension, accompanied with over-activation of the renal renin-angiotensin system (RAS) and AT1R signaling." (PMID 38961282, 2024). "Twelve to 14 weeks of Grk2 knockdown using small hairpin RNA causes a shift toward vasoconstriction and subsequent hypertension." (PMID 38961282, 2024). "A case-control study in Han Chinese showed that the dominant model (CC vs. CT + TT) of rs1894111 polymorphism in the ADRBK1 (GRK2) gene is associated with low-renin hypertension." (PMID 38961282, 2024). "The cardioprotective effects of paroxetine in CH, as well as its effect in mitigating associated hypertension and myocardial infarction, through the inhibition of GRK2 activity, have also been demonstrated." (PMID 38139099, 2023). "In general, GRK2 can break the balance of sodium transport by interfering the function of sodium hydrogen exchangers, Na, K‐ATPases or ENaCs and subsequently causes renal damage leading to hypertension." (PMID 39438268, 2024). "In addition, GRK2 has also been found to play a role in renal vascular reactivity impairment caused by hypertension." (PMID 39438268, 2024). "GRK2 protein expression in lymphocytes is also increased about 2‐fold, and its activity increased >40% in African Americans, a population at higher risk for hypertension and cardiovascular complications compared with other groups." (PMID 27390269, 2016). "In addition, abnormal GRK2 expression or activity is associated with other types of hypertension." (PMID 38961282, 2024). "GRK2 overexpression in VSM may cause inappropriate hypertension and HF, as in CS1." (PMID 37173348, 2023). "Furthermore, a recent study suggested that paroxetine may attenuate hypertension-associated cardiac hypertrophy by blocking GRK2-βAR interaction." (PMID 35155607, 2021). "For example, long-term exercise in SHRs, beginning at the prehypertensive stage (four weeks old), improves vascular insulin sensitivity via down-regulation of vascular GRK2, which limits the progression of hypertension." (PMID 38961282, 2024). "The second, GRK2 can phosphorylate ubiquitin protein ligases and thus disrupt the function of sodium transporters leading to hypertension." (PMID 39438268, 2024). "As for hypertension‐related kidney injury, an increase in GRK2 protein expression in lymphocytes from hypertensive patients, presumably due to the desensitization of β adrenergic receptors that mediated vasodilatation, had been found." (PMID 39438268, 2024). "Third, GRK2-mediated effects in the regulation of blood pressure is complicated, and its role in hypertension needs to be clarified more clearly." (PMID 38961282, 2024). "For instance, researchers have focused on the mechanism of GRK2 in hypertension‐related kidney injury, S‐AKI17 and CRS." (PMID 39438268, 2024). "So GRK2 is currently a well‐established therapeutic target for the treatment of cardiac ischemia, HF, hypertension, insulin resistance and Alzheimer's disease." (PMID 39438268, 2024). "The first, GRK2 can phosphorylate dopamine D1 receptors and thus disrupt the function of sodium transporters leading to hypertension." (PMID 39438268, 2024). "It is also stated that GRK2 has a good chance of inactivating Nedd4 and Nedd4‐2 by phosphorylation, which in turn leads to the overactivation of ENaCs and hypertension." (PMID 39438268, 2024).
Hypertension (continued). "A study based on spontaneously hypertensive rats revealed a possible mechanism of hypertension‐related kidney injury: hypertension resulted in the downregulation of PPARγ and subsequent upregulation of GRK2, which impaired renal vascular reactivity." (PMID 39438268, 2024). "Previous researchers have proposed the use of GRK2 as a potential medicinal approach in cardiovascular disease treatment, such as HF and hypertension." (PMID 34198801, 2021). "The metabolic role of GRK2 is indeed suggested by the animal model of hypertension, such as SHR, where the increased level of the kinase fosters IRES." (PMID 33467677, 2021). "GRK2 expression was shown to be enhanced in hypertension, cardiac hypertrophy, and myocardial infarction, and the inhibition of GRK2 was observed to have beneficial effects on these diseases." (PMID 33806057, 2021). "The expression of GRK2 in myocardial depends on its level in peripheral blood mononuclear cells, likewise upregulation of GRK2 was shown in hypertrophy and hypertension." (PMID 35111168, 2021). "The presence of an altered expression in GRK2 is involved in both human and animal models of hypertension." (PMID 33467677, 2021). "Downregulation of GRK2 induces necroptosis, which then triggers trophoblastic debris, bioactive cytokines into circulation, and finally leads to hypertension and extensive targeted organ damage." (PMID 34917606, 2021). "As another example of lymphocyte GRK2 levels serving as a biomarker in cardiovascular disease, increased GRK2 expression in PBMCs has been reported in patients with hypertension." (PMID 33546162, 2021). "This apparently preferential desensitization by GRK2 of vasodilation versus vasoconstriction signaling has been invoked to explain the effect of upregulated GRK2 levels seen in human and murine hypertension." (PMID 30837878, 2019). "Together, our results indicate the loss of AT1R desensitization following GRK2 knockdown leads to unopposed renal AT1R signaling that result in impaired renal filtration, electrolyte imbalance and hypertension in shGKR2 mice." (PMID 30061705, 2018). "Since a generalized impairment of b-adrenergic mediated vasodilation has been shown both in animal models of hypertension and in human hypertensive subjects, this alteration has been related to the increased GRK2 abundance and activity." (PMID 26911143, 2016). "Anti-GRK2 beads were used to pull-down endogenous GRK2 protein of blood samples from patients with hypertension, and an anti-ubiquitin antibody was used to detect the endogenous GRK2 ubiquitination level." (PMID 27462452, 2016). "GRK5, as with GRK2, for example, is also increased in lymphocytes from hypertensive humans and animal models of hypertension." (PMID 27390269, 2016). "This is indeed the case; however, despite the fact that arterial smooth muscle cells express multiple isoenzymes of the GRK family, only GRK2 expression has been reported to be elevated in both hypertensive patients and in rodent models of hypertension." (PMID 25972452, 2015). "GRK2 regulates the activity of various receptors expressed on renal cells, which may give rise to hypertension‐related kidney injury, S‐AKI, CRS, AKI, age‐related kidney injury, and hyperglycemia‐related kidney injury." (PMID 39438268, 2024). "And the upregulation of GRK2 related to hypertension can impair renal vascular reactivity." (PMID 39438268, 2024). "Additionally, activated renal AT1R-mediated signaling also plays an important role in the development of hypertension after six months of Grk2 knockdown." (PMID 38961282, 2024). "The rebound hypertension in mice that occurs after withdrawal of clonidine, an α1D, α2A-C adrenergic receptor agonist, is mitigated by an increase in nitric oxide bioavailability, an effect that is prevented by suppression of GRK2 activity." (PMID 38961282, 2024).
Hypertension (continued). "This apparent inconsistent effect on blood pressure may be related to the fact that the alteration in GRK2 expression (increased or decreased) can lead to the imbalance of vasoconstrictor and vasodilator effects, resulting in hypertension." (PMID 38961282, 2024). "In addition, increased GRK2 levels and activity were found to be connected with the pathophysiology of HF and hypertension, supporting the pivotal role of GRK2 in cardiovascular diseases." (PMID 39451192, 2024). "The activation of GRK2 by some factors such as oxidative stress and insulin impairs the ability of renal D1R to inhibit sodium transport that leads to the development of hypertension." (PMID 38961282, 2024). "Also, GRK2 has been proven to act as a “gatekeeper” for cardiovascular diseases in a GPCR-independent manner, and GRK2 knockdown in mice results in age-dependent spontaneous hypertension." (PMID 34917606, 2021). "GRK2 is the long-recognized mechanism for agonist-activated G protein-coupled receptor (GPCR) desensitization and internalization; increased GRK2 levels and/or activity have important implications in many cardiovascular conditions, such as myocardial ischemia, hypertrophy, and hypertension." (PMID 30934608, 2019). "Thus, a partial overall GRK2 deletion prevents vascular hypertrophy and increased vessel stiffness observed in the AngII-induced hypertension model." (PMID 30837878, 2019). "In vertebrates, GRK2 hemizygous mice shows the importance of GRK2 in hypertension." (PMID 27022742, 2016). "Indeed, a greater understanding of the contribution of elevated GRK2/arrestin expression to such remodeling processes should clarify the future potential to target these proteins in the clinical management of hypertension." (PMID 25972452, 2015). "Notably, GRK2 is upregulated in the heart and adrenal glands in HF and in vascular tissue during hypertension; strategies that inhibit or inactivate GRK2 in these diseases are very interesting for future human therapy." (PMID 25071591, 2014). "Adrenal GRK2 inhibition could be also positive and valuable as a therapy for other diseases characterized by sympathetic hyperactivity as hypertension, hyperthyroidism, pheochromocytoma or some cognitive, and psychiatric disorders as depression." (PMID 25071591, 2014). "However, a longer (nine months) duration of Grk2 knockdown was reported to lead to a nitric oxide-dependent vasodilation which overcomes vasoconstriction, making Grk2+/− mice resistant to the development of hypertension." (PMID 38961282, 2024). "However, Grk2 deficiency in global adult hemizygous mice does not cause hypertension but impairs the increase in blood pressure and prevents vascular remodeling secondary to Ang II infusion." (PMID 38961282, 2024). "In addition, the mice receiving 4 mg/kg GSK180736A daily from E8.5 to E13.5 and the mice intrauterine injected with GRK2-lentivirus at E8.5 developed PE-like phenotype: new-onset hypertension, proteinuria, and increased serum angiogenic cytokines from E14.5-E18.5." (PMID 34917606, 2021). "As we know GRK2 is upregulated in various kidney diseases, GRK2 inhibition might be an innovative therapeutic strategy to treat renal diseases, such as SLE‐related kidney injury, DN, age‐related kidney injury, hypertension‐related kidney injury, and CRS." (PMID 39438268, 2024). "Interestingly, some recent reports have described that a more profound and global GRK2 knockdown may be detrimental due to enhanced renin- and AT1R-mediated reactive oxygen species (ROS) production that can cause renal damage and the development of hypertension with age." (PMID 30837878, 2019). "We also provided evidence that GRK2 knockdown was accompanied by overactivation RAS and enhanced AT1R-mediated ROS production that can further contribute to the glomerular injury, renal damage and hypertension." (PMID 30061705, 2018).
Hypertension (continued). "In conditions like HF or hypertension with chronically increased SNS and RAAS activity and enhanced GRK2 expression, GRK2 knockdown can influence GPCR signaling by decreasing its phosphorylation state, which in turn attenuates the subsequent β-arrestin binding." (PMID 28759639, 2017). "In addition, GRK2 inhibition may have therapeutic effects in a variety of renal diseases, such as SLE‐related kidney injury, DN, age‐related kidney injury, hypertension‐related kidney injury, and CRS." (PMID 39438268, 2024). "Three different GRK isoforms (GRK2, GRK5 and, in a minor proportion, GRK3) are present in the heart and also in peripheral blood mononuclear cells (PBMC) and their expression (especially GRK2) changes as a consequence of the hemodynamic alterations that occur in HF or hypertension." (PMID 30837872, 2019). "While hypertension is completely reversed by AT1R blockers, defective glomerular filtration is not, suggesting that non-hemodynamic functions related to mesangial proliferation and hypertrophy are altered in the absence of GRK2." (PMID 31432234, 2019).
myocardial infarction (28 papers, 2009 to 2026). Gross necrosis of the myocardium, as a result of interruption of the blood supply to the area, as in coronary thrombosis. "To determine whether reduced GRK2 levels improve cardiac function by directly protecting heart against myocardial I/R injury induced myocyte cell loss we examined post-I/R myocardial infarct size in our two GRK2 KO mice lines." (PMID 23805205, 2013). "For example, the use of paroxetine as a GRK2 inhibitor has been investigated to regulate remodeling after myocardial infarction." (PMID 39857755, 2025). "Previous studies have shown the potential of paroxetine as a GRK2 inhibitor to reverse cardiac remodeling in experimental models of acute myocardial infarction." (PMID 38139099, 2023). "In a mouse model of myocardial infarction with knockdown of β1-adrenergic receptors (β1AR), the inflammatory response was enhanced after GRK2 inhibition." (PMID 35891967, 2022). "Studies have also found that cardiac-specific GRK2 ablation protected the heart from myocardial infarction (MI), reversed pathological left ventricular remodeling, and enhanced Ca2+ handling while diminishing tissue remodeling." (PMID 35430346, 2022). "Cardiomyocyte-specific knockout of GRK2 demonstrated that GRK2 ablation protects the heart against cardiac dysfunction and fibrosis, following myocardial infarction." (PMID 34359886, 2021). "An increase in GRK2 expression predominantly in endothelial cells was reported in the heart of rats 7 days after induction of myocardial infarction." (PMID 30837878, 2019). "On the other hand, augmented GRK2 levels have been reported in peripheral blood samples in HF or acute myocardial infarction patients, but the potential pathophysiological impact of such altered dosage remains to be determined." (PMID 30837878, 2019). "Recent studies from our lab have shown that silencing myocardial GRK2 expression or preventing GRK2 activity (with a peptide inhibitor) can prevent or rescue HF progression after myocardial infarction." (PMID 23805205, 2013). "We crossed β1AR knockout (B1KO) mice with cardiac-specific transgenic mice expressing the βARKct, a known GRK2 inhibitor, and studied the offspring under normal conditions and in post-myocardial infarction (MI)." (PMID 23984976, 2013). "In a mouse model of post-myocardial infarction HF, it was found that treatment with the selective serotonin reuptake inhibitor paroxetine may inhibit GRK2 and promote βAR-mediated cardiomyocyte contractility." (PMID 40076919, 2025). "Interestingly, SHP2 exerts a protective effect in myocardial resurgence post-myocardial infarction by inhibiting the GRK2/SMAD/ERK pathway." (PMID 39101141, 2024). "GRK2 levels may reflect hemodynamic impairment and might have a meaningful prognostic value after myocardial infarction." (PMID 36213457, 2022). "In vivo, paroxetine has been described to improve LV function and structure and to reverse or even ameliorate several features related to cardiac dysfunction in a mouse model of myocardial infarct when compared with fluoxetine, a structural analog unable to inhibit GRK2 but with SSRI capacity." (PMID 30837878, 2019). "Thus, paroxetine-mediated inhibition of GRK2 enhances cardiac performance, reverses sympathetic overstimulation, normalizes the myocardial βAR functions, and protects the heart after myocardial infarction (MI)." (PMID 30538631, 2018). "Interestingly, reduction in sympathetic activity via adrenal-targeted G-protein-coupled receptor kinase 2 (GRK2) gene deletion attenuates HF progression and improves cardiac function after myocardial infarction." (PMID 27402067, 2016). "When β-adrenoreceptor responsiveness was examined in a completely developed reperfused myocardial infarction model, higher levels of tissue catecholamines and GRK2 were observed in the ischemic epicardium, leading to sympathetic overstimulation of the failing heart." (PMID 20204079, 2009).
myocardial infarction (continued). "White cell GRK2 levels have been reported to also increase in acute ST segment elevation in myocardial infarction (MI) patients and to predict post-MI cardiac remodeling." (PMID 33669936, 2021). "In myocardial infarction-related I/R models, S-nitrosylation of Trx, PAF, GRK2, CypD, and the ND3 subunit of mitochondrial complex I reduces infarct size and protects the heart from I/R injury, while S-nitrosylation of sEH exacerbates I/R damage." (PMID 40867518, 2025).